FGF21 (fibroblast growth factor 21)
Diseases named in the same sentence as FGF21 in open-access papers (continued):
Sharing a sentence is not in itself a finding about the gene and the disease.
liver disease (54 papers, 2011 to 2026). "Seipin deficiency leads to metabolic-associated steatotic liver disease and dysregulated FGF21 signalling." (PMID 41465464, 2025). "FGF21 and adiponectin emerged as key mediators, showing interconnected patterns and similar associations with metabolic health and liver disease." (PMID 40943431, 2025). "MASH and MAFLD has been associated with a FGF21-resistant state rendering FGF21 and its analogues as effective therapeutic options for liver disease." (PMID 40522819, 2025). "In metabolic-associated steatotic liver disease, elevated circulating and hepatic FGF21 levels have been interpreted as a compensatory response to hepatocellular injury." (PMID 41465464, 2025). "In this review article, we attempt to concisely explain the role of FGF21 and its mutations and analogs on liver disorders." (PMID 36457562, 2022). "Using a comprehensive panel of circulating organokines, including fibroblast growth factor (FGF) 19, FGF21, adiponectin, galectin-3, irisin, and leptin, along with choline metabolites, we characterized metabolic signaling patterns associated with liver disease severity." (PMID 40943431, 2025). "Since FGF21 can be considered a marker of ER stress, it can be used as an efficient diagnostic biomarker for a variety of diseases including alcoholic cardiomyopathy, muscle dysfunction, and liver diseases like NAFLD108 and HCC." (PMID 38292187, 2024). "Given that FGF21 dysregulation has been described in lipodystrophic patients and in seipin-deficient mice, we aimed to characterize the hepatic FGF21 pathway in our models to better understand its potential role in the pathogenesis of seipin-related liver disease." (PMID 41465464, 2025). "CONCLUSIONS: Genetic variation in GCKR and FGF21, together with altered hepatokine signaling, contributes substantially to metabolic dysregulation and liver disease severity." (PMID 41975319, 2026). "Recently, studies reported increased FGF21 levels in patients with advanced liver disease, including decompensated liver cancer." (PMID 40242310, 2025). "Post-intervention correlations among FGF-21, autophagy markers, and liver disease parameters were examined." (PMID 40430125, 2025). "However, the mechanisms underlying the role of FGF21 in liver disease remain unclear." (PMID 40604130, 2025). "This review summarizes the mechanism of FGF21-mediated autophagy and its derived application in the defense of stress in liver diseases and offers a glimpse into its promising prospect in future clinical practice." (PMID 38292187, 2024). "Fibroblast growth factor 21 (FGF21) is another regulator connecting autophagy and senescence in the pathogenesis of liver diseases." (PMID 38069199, 2023). "Further studies will be required to determine the effectiveness and accuracy of FGF21 and its analogs in targeted therapy to cure and diagnose hepatic disorders." (PMID 36457562, 2022). "In conclusion, FGF21 continues to emerge as an interesting tool for the study and precise understanding of metabolic and liver diseases." (PMID 36362103, 2022). "Our study offers a potential strategy for enhancing the efficacy of FGF21 for the treatment of liver diseases." (PMID 36703750, 2022). "It remains to be clarified if the upregulation of Fgf21 in the offspring of obese mothers is a mere consequence of liver disease or plays an active role in its development." (PMID 35203502, 2022). "To date, a large body of evidence expanded the role of FGF21 as biomarker of several liver diseases." (PMID 30692965, 2018).
liver disease (continued). "Secondly, the sample size of patients with HBV-related liver diseases was relatively small, especially for patients with HCC, which limited the further analysis to find out a diagnostic cutoff of serum FGF21 level." (PMID 29184085, 2017). "We next investigated the changes of serum FGF21 in chronic HBV infected patients with advanced liver diseases." (PMID 29184085, 2017). "Our analyses of liver tissue sections from human patients with diverse liver diseases further confirmed the notion that FGF21 is a potential biomarker of human liver diseases." (PMID 23590285, 2013). "FGF21 levels also correlate with gamma-glutamyl transferase(γ-GT) and aspartate aminotransferase(AST), indicating the close relationship between FGF21 and liver diseases." (PMID 21949781, 2011). "This imbalance in the FGF21-adiponectin axis may be crucial for liver health, though liver disease itself may also contribute to this dysregulation." (PMID 40943431, 2025). "Thus, FGF21, alongside its analogs, presents a compelling case for exploration in the treatment of liver diseases, particularly for conditions characterized by metabolic dysregulation." (PMID 40806358, 2025). "In older patients, however, advanced liver changes might lead to higher FGF21 production as a response to damage like in another liver disease." (PMID 39941067, 2025). "Human patients with liver disease exhibit an activation in the FGF21 pathway, potentially as a protective response, which suggests that circulating FGF21 levels might be useful as a biomarker for hepatic disease." (PMID 38535834, 2024). "This could provide relevant data on how to exploit FGF-21 as a potential marker of liver disease and as a therapeutic strategy." (PMID 37999215, 2023). "Recently, several studies have demonstrated a correlation between FGF21 and liver diseases." (PMID 36457562, 2022). "Consequently, due to the importance of circulatory FGF21 concentration the SNPs regulating the serum level of FGF21 are considerably crucial in liver diseases." (PMID 36457562, 2022). "These clinical trials on FGF21 analogs and mimetics showed that they could be used as potential therapeutic agents for metabolic and liver disorders." (PMID 36457562, 2022). "We next asked whether rs838133 affects the relative change in FGF21 between healthy and metabolic liver disease subjects." (PMID 34141520, 2021). "Fibroblast growth factor 21 (FGF21) is identified as a potential biomarker for liver diseases." (PMID 30692965, 2018). "Chronic HBV infection may progress to HBV-related liver diseases including cirrhosis, acute-on-chronic liver failure (ACLF) and HCC3, but the association between hepatic FGF21 expression and the progression of those diseases is largely unknown." (PMID 29184085, 2017). "In this survey-based study, we examine the nature of hepatic FGF21 activation in liver tissues and tissue sections from several mouse liver disease models and human patients, by quantitative PCR, immunohistochemistry, protein chemistry, and reporter and CHIP assays." (PMID 23590285, 2013). "In the case of liver disease, these regulatory mechanisms may be impaired, leading to excessive FGF21 production, even without stimuli that would normally cause it." (PMID 39941067, 2025). "Taken together with other studies, we conclude that FGF21 is an indicator of liver function and stress, and has the potential to be a predictive biomarker for liver function test, early diagnosis of liver cancer, other hepatic diseases and minimally-invasive clinical analysis." (PMID 23590285, 2013). "This indicates that serum FGF21 may be an excellent minimally-invasive biomarker that is sensitive, specific and of predicative value for test of liver function and diagnosis of the onset, stage and prognosis of various liver diseases." (PMID 23590285, 2013).
liver disease (continued). "Differences in correlations with basic biochemical parameters depending on the primary liver disease suggest unique functions of FGF19 and FGF21 in various clinical contexts." (PMID 39941067, 2025). "As is the case for GDF-15, elevated circulating levels of FGF-21 does not specifically point to a diagnosis of mitochondrial disorders but can also be observed in other conditions, most notably in liver disorders." (PMID 36361969, 2022). "It has been recently demonstrated that ChREBP loss of function is essential for the fructose-dependent increase of plasmatic levels of FGF21, and that under high-fructose diets an absence of FGF21 leads to liver disease." (PMID 30893897, 2019). "As a heptokine, FGF21 was widely studied in NAFLD and other liver diseases." (PMID 30692965, 2018). "Serum FGF21 levels were measured in 33 acute hepatitis B (AHB), 75 chronic hepatitis B (CHB) and 66 CHB patients with advanced liver diseases including liver cirrhosis, acute-on-chronic liver failure (ALCF) and hepatocellular carcinoma (HCC) together with 200 age- and BMI-matched healthy controls." (PMID 29184085, 2017). "FGF21 analogs, such as pegbelfermin, have demonstrated effectiveness in increasing hepatic fatty acid oxidation (FAO), reducing lipotoxicity, and preventing fibrosis in metabolic disease models, highlighting their potential application in treating cirrhosis and other liver disorders." (PMID 40806358, 2025). "A healthy liver maintains FGF21 concentration at a lower level because there is no need for its increased production; there is no need to support the body’s defense mechanisms or counteract the metabolic disorders characteristic of liver diseases." (PMID 39941067, 2025). "By discussing the crosstalk between GLP1-Ras-FGF21-fetuin-A, this review hypothesizes that the possible modulation of fetuin-A by the novel GLP1-FGF21 dual agonist pharmacotherapy may contribute to the management of metabolic and liver diseases." (PMID 39409124, 2024). "Among the PCOS patients, the FGF21 concentrations were significantly higher in those with NAFLD, whereas a 1 pg/mL increase in the FGF21 concentration increased the odds of NAFLD by 1%, suggesting FGF21 as a potential biomarker for hepatic disease in females with PCOS in adolescence." (PMID 37685811, 2023). "Additionally, patients with alcoholic steatohepatitis had FGF21 levels 6 times greater than non-drinking healthy subjects without any liver diseases." (PMID 36457562, 2022). "Additionally, the efficacy of an FGF21 analogue on bile duct ligation-, and in alcohol- and virus- induced liver diseases in mice with different etiologies of liver injury has not been well elucidated." (PMID 29444136, 2018). "Thus, the elevation in blood FGF21 levels is not specific to liver disease, and other confounding factors affecting serum FGF21 levels should be considered as a limitation for the prediction of hepatic I/R injury." (PMID 26806156, 2016). "Higher plasma FGF21 levels in younger PBC patients compared to older ones before transplantation, alongside the absence of similar differences in other liver diseases, suggest unique characteristics specific to this condition." (PMID 39941067, 2025). "Surprisingly, we have not shown a substantial difference in FGF21 levels among subjects with or without NAFLD in our cohort, which could possibly be attributed to different stages of liver disease at baseline in patients with NAFLD in this cohort." (PMID 33071964, 2020).
heart failure (50 papers, 2015 to 2026). Inability of the heart to pump blood at an adequate rate to meet tissue metabolic requirements. "Further research is necessary to more accurately determine the diagnostic and prognostic value of NLR and FGF21 in relation to left ventricular diastolic dysfunction and heart failure among patients with rheumatoid arthritis." (PMID 41464745, 2025). "Recent studies have linked FGF21 levels to left ventricular diastolic dysfunction, HFpEF, and have reported predictive utility in dilated cardiomyopathy and heart failure with reduced ejection fraction (HFrEF)." (PMID 41464745, 2025). "GATM converts taurine and arginine into phosphagen taurocyamine, which, together with uridine, stabilizes the ETC and improves heart failure; all these metabolites were altered in FGF21-deficient serum." (PMID 40998786, 2025). "FGF21 was found to be an independent risk factor for the development of heart failure during hospitalization in STEMI patients by binary logistic regression analysis." (PMID 36778154, 2023). "Elevated serum FGF21 levels are an independent risk factor for the development of heart failure during hospitalization in STEMI patients and have predictive value." (PMID 36778154, 2023). "The aim of this study was to evaluate the roles of fibroblast growth factor 21 (FGF21) in heart failure patients with reduced ejection fraction and its association with Heart Failure with reduced Ejection Fraction (HFrEF)." (PMID 35069790, 2022). "In our study, we showed the association between circulating FGF21, LV hypertrophy, and diastolic dysfunction in heart failure subjects." (PMID 27650781, 2016). "Although a causal relationship to SPP-004 could not be excluded, it was strongly suggested that the death was due to heart failure caused by the underlying disease, considering that this case was the most severe with an extremely high blood FGF21 level." (PMID 40868816, 2025). "While increased serum levels of FGF21 are generally associated with physiological states such as veganism or exercise, cardiac Fgf21 expression is described to be enhanced by pathological stimuli, such as diabetic cardiomyopathy and heart failure." (PMID 39770968, 2024). "Finally, analysis of mRNA expression in hearts from Akita mice showed an upregulation in expression of a number of genes associated with heart failure, including Nppa, Nppb, Gdf15, Fgf21 and Myh7." (PMID 32979176, 2020). "Moreover, hepatic congestion associated with heart failure with preserved ejection fraction (HFpEF) induces hepatic FGF21 expression, which in turn regulates cardiac metabolism as part of a compensatory protective mechanism—constituting a protective feedback loop between organs." (PMID 41234361, 2025). "Subsequently, we found that FGF21 was the most notably increased secretory protein that mediated the effects of hepatocyte MR deficiency and spironolactone in post-MI mice and/or patients with heart failure (HF) and dissected the regulatory mechanisms of MR on Fgf21." (PMID 37018396, 2023). "Our findings that βOHB and FGF21 activate AMPK/PGC1α/PPARα signaling, and loss of FGF21 exaggerates serum βOHB elevation and promotes oxidative stress response in the heart contribute to the understanding of pathophysiological aspects of elevated serum βOHB and FGF21 in heart failure." (PMID 35513524, 2022). "Elevated circulating FGF21 levels have been observed not only in patients with heart failure but also in those with coronary heart disease." (PMID 41234361, 2025). "A further study revealed that the expression of fibroblast growth factor receptor 1 (FGFR1) and FGF21 was opposite in heart failure." (PMID 41173187, 2025). "Other myokines whose activity is related to heart failure but originate from tissues other than muscle include the following: interleukins 8 and 15 (IL-8, IL-15) and fibroblast growth factor 21 (FGF-21)." (PMID 39203852, 2024).
heart failure (continued). "Elevated serum FGF21 levels have been shown to be a strong predictor of heart failure during hospitalization in patients with STEMI after emergency PCI." (PMID 36778154, 2023). "The FGF21 has a similar role to NT-proBNP in predicting the development of heart failure during hospitalization in STEMI patients." (PMID 36778154, 2023). "In this study, we observed that serum FGF21 levels were associated with NT-proBNP in STEMI patients after emergency PCI and were elevated in STEMI patients who developed heart failure during hospitalization." (PMID 36778154, 2023). "The univariate Logistic regression analysis found that LDL-C, HDL-C, troponin I, NT-proBNP, FGF21, LAD, LVEDD, LVESD, LVESV, LVM, LVEF were associated with heart failure during hospitalization in STEMI patients (P < 0.05)." (PMID 36778154, 2023). "Serum circulating FGF-21 have also been found to be elevated in patients with heart failure with reduced ejection fraction and to correlate with BNP levels." (PMID 37484982, 2023). "The area under curve (AUC) for FGF21 to predict the development of heart failure during hospitalization in STEMI patients was 0.816 (95% CI [0.770–0.863]) according to the receiver operating characteristic (ROC) curve analysis." (PMID 36778154, 2023). "In clinics, myocardial FGF21 is increased in advanced heart failure; however, in a pre-clinical ischemic mouse heart, FGF21 induction is not apparent." (PMID 35983184, 2022). "Previous studies have shown that the level of FGF21 in plasma is related to the diastolic dysfunction of the heart, especially in patients with heart failure with preserved ejection fraction." (PMID 35069790, 2022). "In up to 20% of heart failure patients with reduced EF, which is accompanied by an inflammatory losing weight syndrome, namely cardiac cachexia, the serum level of FGF21 is also increased." (PMID 34095143, 2021). "The Kaplan–Meier analysis demonstrated a significant difference in 1-year mortality (log rank p = 0.0031) and 1-year heart failure readmission events (log rank p < 0.0001) between subjects grouped by FGF21 value." (PMID 27650781, 2016). "Biomarkers like FGF-21 and galectin-3 could provide greater insight into heart failure severity, especially in diabetic patients." (PMID 39597026, 2024). "As a regulator of cardiomyocyte mitochondrial homeostasis under oxidative stress, FGF21 could be an important new target for therapeutic options for patients with heart failure." (PMID 37156793, 2023). "We selected FGF21 and NT-proBNP, a classical marker of heart failure, for ROC curve analysis." (PMID 36778154, 2023). "However, after logistic regression analysis, FGF21 was found to have a similar effect to NT-proBNP in predicting the development of heart failure during hospitalization in STEMI patients." (PMID 36778154, 2023). "Moreover, serum FGF21 levels were also significantly elevated in patients with Heart failure with preserved ejection fraction (HFpEF) and end-stage heart failure." (PMID 36778154, 2023). "The multivariate logistic regression analysis found that the elevated levels of NT-proBNP and FGF21 and decreased levels of LVEF may be independent risk factors for heart failure during hospitalization in STEMI patients (P < 0.05)." (PMID 36778154, 2023). "This suggests that measuring serum FGF21 levels could be a useful biomarker for predicting outcomes in patients with heart failure." (PMID 37484982, 2023). "Therefore, this study intends to investigate the correlation between serum FGF21 levels and heart failure during hospitalization in STEMI patients treated with emergency PCI by measuring serum FGF21 levels." (PMID 36778154, 2023). "Our findings that βOHB and circulating FGF21 control oxidative stress response induced by nutrient stress open new possibilities of βOHB and FGF21 for potential pharmacological intervention for heart failure in which elevated ROS production is believed to play a key role." (PMID 35513524, 2022).